NPY (neuropeptide Y)
Diseases named in the same sentence as NPY in open-access papers (continued):
Sharing a sentence is not in itself a finding about the gene and the disease.
heart failure (23 papers, 2017 to 2025). Inability of the heart to pump blood at an adequate rate to meet tissue metabolic requirements. "In heart failure patients undergoing cardiac resynchronisation implantation, elevated CS NPY concentrations are associated with major adverse cardiac events." (PMID 38847435, 2025). "Elevated levels of NPY are implicated in a range of cardiovascular diseases including stress‐induced cardiomyopathy, heart failure and myocardial infarction." (PMID 37460913, 2023). "PV NPY as a continuous variable was associated with heart failure or death, with an estimated hazard ratio (HR) of 1.014 (95% CI, 1.006–1.022; P<0.001)." (PMID 35766271, 2022). "In contrast, NPY can be measured easily and safely from a peripheral vein, and the major finding of the present study is that high levels of PV NPY are associated with the development of heart failure or death after reperfusion." (PMID 35766271, 2022). "Kaplan‐Meier survival analysis demonstrated that high PV NPY levels (>21.4 pg/mL by binary recursive partitioning) were associated with increased incidence of heart failure and mortality (hazard ratio, 3.49 [95% CI, 1.65–7.4]; P<0.001)." (PMID 35766271, 2022). "Is the adrenergic cotransmitter neuropeptide Y (NPY) associated with outcomes in patients with stable heart failure (HF)?" (PMID 31876927, 2020). "Here, we discuss recently published data demonstrating that peripheral venous NPY levels are associated with heart failure hospitalisation and mortality after AMI, and all cause cardiovascular mortality in CHF, even when adjusting for known risk factors (including brain natriuretic peptide)." (PMID 38847435, 2025). "High PV NPY levels, which are easy to obtain and measure following coronary intervention, are independently associated with subsequent heart failure and death and could prove to be a useful biomarker in risk stratifying these patients." (PMID 35766271, 2022). "Moreover, high PV NPY levels are associated with subsequent heart failure and mortality, even after adjustment for age and cardiovascular risk factors." (PMID 35766271, 2022). "PV NPY levels are associated with the subsequent development of heart failure or mortality and may therefore be a useful prognostic marker." (PMID 35766271, 2022). "Given that the most pragmatic measurement to obtain clinically is PV NPY, we sought to ascertain whether this was associated with the development of heart failure or death in the OxAMI (Oxford Acute Myocardial Infarction) Study." (PMID 35766271, 2022). "Kaplan‐Meier survival analysis demonstrated that high PV NPY levels are associated with an increased incidence of death (HR, 3.07 [95% CI, 1.18–7.97]; P=0.02), heart failure (HR, 6.16 [95% CI, 2.04–18.6]; P<0.001), or both (HR, 3.49 [95% CI, 1.65–7.4]; P<0.001)." (PMID 35766271, 2022). "This fairly modest increase may represent the increase in NPY during mild chronic stress or due to genetic variants, but not the high levels that have been associated with poor survival in heart failure patients." (PMID 31811615, 2020). "Different mechanisms that may mediate the association of dysregulated NPY signaling and heart failure have been suggested." (PMID 30283345, 2018). "However, we do not feel that a lack of a control group diminishes the new and clinically relevant finding that HRR, which is strongly associated with prognosis in heart failure, is correlated with NPY levels during CPET, which is an important finding in its own right." (PMID 39861963, 2025). "Stellate ganglia from patients with heart failure show decreased NPY immunoreactivity despite unchanged NPY mRNA expression, implying increased release of NPY to the heart." (PMID 38847435, 2025). "The sympathetic co-transmitter neuropeptide Y (NPY) is a promising biomarker for sympathetic hyperactivity following myocardial infarction and heart failure." (PMID 41511320, 2025). "It has also been found that in patients with heart failure, NPY ≥ 130 pg/mL indicates a worse outcome." (PMID 37240956, 2023).
heart failure (continued). "We therefore assessed the prognostic value of PV NPY during follow‐up, where 34 patients (20.7%) developed heart failure or died." (PMID 35766271, 2022). "We provide here the first evidence that the protein expression of DPP4 and NPY decreased in cardiac tissue samples of heart failure patients." (PMID 35884882, 2022). "Here, we showed that the protein expression of DPP4 and NPY decreased in the cardiac tissue of heart failure patients." (PMID 35884882, 2022). "It is interesting to note that with our data, the relationship between high PV NPY and heart failure or mortality is lost during multivariable Cox regression analysis after adjustment for coronary flow reserve, LGE extent, and LVEF at 6 months (P=0.41)." (PMID 35766271, 2022). "In the case of sympathetic nerve pathology caused by myocardial infarction, left ventricular hypertrophy, and heart failure, NPY is released from the sympathetic nerve of the heart with increasing level of the plasma NPY." (PMID 34471416, 2021). "The hyperproliferation of sympathetic nerve endings will release a large amount of catecholamines and neuropeptides (NE, NPY), which can promote cardiac hypertrophy and ventricular hypertrophy, ultimately leading to heart failure and sudden death." (PMID 34471416, 2021). "EECs play an important role in cardiac pathological processes, such as excitation-contraction coupling, arrhythmia, cardiac hypertrophy, and heart failure, by secreting cardiac active factors, such as NPY and ET-1." (PMID 34512386, 2021). "In man, several studies already reported that plasmatic NPY levels rise following acute coronary syndromes and in heart failure, showing a positive correlation with severity of heart failure and 1 year mortality." (PMID 30972341, 2019). "A more recent study has also confirmed higher NPY levels in heart failure patients, which correlated with BNP levels and echocardiographic markers of heart failure severity." (PMID 30283345, 2018). "Other small studies have only found a trend for elevated NPY levels for example in heart failure patients undergoing invasive haemodynamic studies in response to dobutamine, and in response to exercise." (PMID 30283345, 2018). "We speculate that given that NPY levels can also increase in heart failure patients, a similar delayed rise in NPY3–36 during recovery would also be seen." (PMID 39861963, 2025). "This greatly strengthens previous assumptions that NPY levels are indeed elevated in heart failure." (PMID 39861963, 2025). "Following STEMI, plasma NPY levels are independent predictors of heart failure and death." (PMID 38847435, 2025). "Cardiac expression of DPP4 and NPY decreased in heart failure patients." (PMID 35884882, 2022). "Using the same assay, we have also recently shown in patients with severe heart failure undergoing implantation of cardiac resynchronization therapy devices, that coronary sinus levels of NPY are significantly higher than in the STEMI population and are strongly associated with mortality." (PMID 31834357, 2020). "Circulating NPY level is higher in patients with MI and heart failure than the control subjects." (PMID 31708788, 2019). "As well as changes in NPY levels, the same study found a shift in mRNA from the Y1R to the Y2R in heart failure, and this may represent another way in which differential effects are mediated." (PMID 30283345, 2018). "Early studies showed high baseline levels in heart failure patients, and indeed there is evidence that severity of heart failure may be correlated to NPY level." (PMID 30283345, 2018). "The ability to further increase NPY release in patients with heart failure, may be related to the severity of the condition." (PMID 30283345, 2018). "Our findings are in line with previous data showing that cardiac tissue NPY protein expression is decreased in rats with volume-overload-induced heart failure, while in parallel, these studies revealed that the circulating level of NPY is increased due to heart failure." (PMID 35884882, 2022).
heart failure (continued). "In addition, there is evidence that NPY activates rat cardiac fibroblasts, an effect blocked by Y1R antagonist, and cardiac fibroblasts are known to be key to cardiac remodeling and fibrosis and are thus central to the pathogenesis of heart failure." (PMID 30283345, 2018). "A high cardiac output model of heart failure in the rat found high plasma levels but reduced tissue levels in the heart although this may be as a result of increased cardiac release of NPY." (PMID 30283345, 2018). "In spite of this, increased NPY levels may also play a protective role in heart failure." (PMID 30283345, 2018). "The mechanism proposed for increased incidences of cardiac failure hospitalization was related to elevated concentration of the DPP4 substrates, substance P and Neuropeptide Y, both of which increase heart rate by increasing sympathetic activity." (PMID 39861115, 2025). "Thirdly, peak NPY levels and the ability to increase NPY levels during exercise were positively correlated with HRR, a known prognostic indicator for reduced mortality in the heart failure population." (PMID 39861963, 2025). "Studies using less specific assays, prior to the advent of modern heart failure therapies, have found no increase or a small increase in peripheral venous NPY concentrations during exercise." (PMID 39861963, 2025). "In two studies which measured NPY levels in heart failure patients post-exercise, one found no significant increase, whilst one found an increase from 50+/−5 to 60+/−6 pmol/l." (PMID 30283345, 2018). "To examine whether the early death of NPY−/− CR mice was promoted by heart failure, we evaluated mRNA levels of cardiac injury and stress genes in heart tissue of NPY+/+ CR and NPY−/− CR mice." (PMID 28101970, 2017). "We propose NPY as a new mechanistic biomarker in AMI and CHF patients and aim to determine whether specific NPY receptor blockers can prevent arrhythmia and attenuate the development of heart failure." (PMID 38847435, 2025). "Mechanistically, this is consistent with the hypothesis that NPY contributes to microvascular dysfunction and subsequent infarct size, leading to heart failure and mortality following STEMI, rather than having other independent effects outside that of influencing infarct size." (PMID 35766271, 2022).
migraine (23 papers, 2016 to 2025). "Given that the NPY is also a potent neuromodulator playing roles in analgesia and antianxiety effects, changed NPY expression in the MHb by GTN might be the cause of GTN-induced migraine-like phenotypes." (PMID 37231359, 2023). "Studies focusing on evaluating the NPY levels in plasma found an increase during attacks in migraine patients with aura and, to a lesser extent, in those without it." (PMID 38397400, 2024). "The craniocervical blood vessels, of great relevance in the etiopathology of migraine, are innervated by sympathetic fibers from the cervical and stellate ganglions that store and release neuropeptide Y (NPY)." (PMID 38397400, 2024). "All of these processes are known to be involved in migraine, suggesting a key role of NPY in migraine pathophysiology." (PMID 37231359, 2023). "Subsequently, a rat model of migraine using repeated electrical stimulation of the trigeminal ganglion revealed increased NPY levels (as well as CGRP, PACAP, and VIP) in both trigeminal ganglion and blood." (PMID 37569369, 2023). "Considering the widespread expression of NPY in the brain, a deeper understanding of its variations in brain areas and its specific role in migraine is urgently needed." (PMID 37231359, 2023). "In accord, elevated NPY plasma levels were reported in an animal model of migraine after the electrical stimulation of the trigeminal ganglion." (PMID 36982428, 2023). "A recent preclinical study reported on dynamic changes in NPY using a rat model where migraine was induced by electrical stimulation of the trigeminal ganglia (TG)." (PMID 37231359, 2023). "Unlike previous research, in the current study, we determined whole-brain NPY expression levels using VISoR imaging and a well-accepted migraine mouse model." (PMID 37231359, 2023). "Further elevations were observed upon repeated stimulation, confirming the important role of NPY in migraine pathogenesis." (PMID 37231359, 2023). "Unfortunately, studies that examined NPY changes in patients with migraine produced highly variable findings." (PMID 37231359, 2023). "Our data provide the first evidence that NPY signaling through the Y1 receptor in the MHb critically modulates migraine-like behaviors." (PMID 37231359, 2023). "Given the links between these physiological mechanisms and migraine, NPY has been of interest in migraine." (PMID 37569369, 2023). "Higher CSF NPY levels have been found in subjects with migraine during the ictal period compared with HC." (PMID 36982428, 2023). "A research group reported that the NPY immunoreactivity was higher in patients with migraine during attacks in the CSF." (PMID 35328439, 2022). "According to some immunohistochemical investigations, the locus coeruleus acts as a “migraine generator”, containing the C-terminal flanking peptide of NPY immunoreactivity in the neurons." (PMID 35328439, 2022). "This is mainly due to the incremented levels of pro-inflammatory agents (Neuropeptide Y (NPY), CGRP) that are associated with abdominal obesity and blamed to be in association with the pain manifestation in those individuals with migraine." (PMID 35222662, 2022). "Glutamate and neuropeptide Y (NPY), neurotransmitters linking the gut–brain axis, are elevated during migraine attacks and play a role in migraine pathophysiology." (PMID 35409704, 2022). "Several previous studies have shown that peptides from prohormones such CGRP (in plasma and TG), NPY (in dorsal root ganglia and DH), and PENK/POMC (in H) are directly associated with migraine and other pain states." (PMID 31649062, 2019). "Consistent with previous findings, we observed increases in plasma levels of vasoactive neurotransmitters (except NPY) in migraine rats." (PMID 31217804, 2019).
migraine (continued). "The premonitory symptoms in migraine such as changes in appetite have been proposed to involve NPY and NPY has been demonstrated in human cranial vessels, reflecting its role in controlling cranial vasculature and its implication in migraine pathogenesis." (PMID 29442286, 2018). "Plasma NPY levels in migraine patients taking flunarizine or amitriptyline were markedly increased, with the highest levels during the second and third months." (PMID 29442286, 2018). "Plasma NPY levels tended to significantly increase during attacks in patients with migraine with aura." (PMID 29442286, 2018). "In vivo electrophysiology in migraine animal model shows that neuropeptide Y dose dependently inhibits dural-evoked trigeminal activity, through NPY Y1 receptor activation." (PMID 27023421, 2016). "This study demonstrates that NPY dose dependently inhibits dural-evoked trigeminal activity, through NPY Y1 receptor activation, indicating antinociceptive actions of NPY in a migraine animal model." (PMID 27023421, 2016). "Our findings reveal a potential involvement of NPY in migraine pathophysiology, through its ability to modulate the firing of dural-evoked nociceptive second-order trigeminovascular neurons." (PMID 27023421, 2016). "Recently, NPY signaling was shown to be involved in migraine via NPY receptor type 1 (Y1R)." (PMID 38397400, 2024). "Unfortunately, potential relationships between NPY levels and migraine remain uncertain." (PMID 37231359, 2023). "Orexins have been implicated in migraine biology, and orexin A reduces TCC firing in a rodent model of migraine and also promotes NPY release, so these neuropeptides are likely to anatomically and functionally interact in physiological and perhaps migraine pain mechanisms." (PMID 37569369, 2023). "In migraine-affected women, increased fasting neuropeptide Y levels in migraine may be a factor leading to increased insulin resistance due to specific alterations in energy intake and sympathetic–adrenal system activation." (PMID 37886939, 2023). "In addition, NPY has roles in sleep and shortens sleep latency in humans and in response to stress and mood, providing possible links between migraine and altered physiological processes that are commonly reported by patients." (PMID 37569369, 2023). "Therefore, the purpose of this study was to investigate the role of NPY in migraine-like phenotypes." (PMID 37231359, 2023). "Thus, we used GTN to model migraine in mice and investigated the role of NPY in migraine-like phenotypes." (PMID 37231359, 2023). "The association between NPY levels and migraine has been extensively studied; however, no conclusions were reached." (PMID 37231359, 2023). "Till date, the specific roles of NPY in migraine and how it functions after migraine onset remain unclear." (PMID 37231359, 2023). "Moreover, further studies will be needed to examine other potentially implicated brain regions, including the SPVO, NPC, PGRN, GU5, and SSp-n5, and determine how the NPY system contributes to migraine symptoms." (PMID 37231359, 2023). "Changes in NPY levels have been found in patients with migraine, but whether and how these changes contribute to migraine is unknown." (PMID 37231359, 2023). "Several data suggest that NPY plays a role in the pathophysiologic mechanism of migraine with aura." (PMID 35328439, 2022). "However, clinical trials are warranted to ascertain the therapeutic promise of targeting NPY signaling in migraine." (PMID 36514014, 2022). "Thus, we have more confidence to conclude that the PACAP and NPY expression levels are significantly enhanced in the migraine model." (PMID 34963819, 2021). "As of yet, no drugs have been developed specifically or otherwise applied to targeting the NPY system in migraine; however, preclinical studies antagonizing the Y1 receptor show that this may prove to be a potential therapeutic target." (PMID 29442286, 2018).